CMKLR1 (chemerin chemokine-like receptor 1)
Diseases named in the same sentence as CMKLR1 in open-access papers (continued):
Sharing a sentence is not in itself a finding about the gene and the disease.
tumor (63 papers, 2014 to 2025). "The increased expression of CMKLR1 has also been shown in tumor-associated macrophages, again suggesting a role for CMKLR1 in regulating tumor growth." (PMID 40564073, 2025). "CCRL2 is highly expressed in the tumor microenvironment and various human cancers, and its expression has been linked to delayed tumor growth in mouse models, primarily through the chemerin/CMKLR1 axis." (PMID 40867595, 2025). "The activity of CMKLR1 and chemerin is also associated with the stimulation of tumor invasion in esophageal cancer." (PMID 34946244, 2021). "Chemerin-deficient mice had accelerated tumor growth and impaired recruitment of tumor-infiltrating NK cells that express CMKLR1." (PMID 34068679, 2021). "In mice, coculturing macrophages with tumor cells caused an upregulation of CMKLR1, and, when treated with chemerin, there was increased expression of proinflammatory mediators." (PMID 29279348, 2018). "The data consistently showed that chemerin targeted tumor cells and tumor-associated endothelial cells, the major source of GM-CSF and IL-6, via interaction with CMKLR1 and CCRL2, reducing expression of inflammatory cytokines and inhibiting NF-κB activation." (PMID 30555465, 2018). "Tumor CMKLR1 was associated with the T stage, vessel invasion, histologic grade and UICC stage." (PMID 36979716, 2023). "Importantly correlation analyses showed significant co-expression between CMKLR1 and genes specific of tumor associated macrophages (TAM) such as CD14, CD163, MRC1 and HLA-DRA in BC and MPM." (PMID 37539056, 2023). "This, in turn, activates CMKLR1-expressing cells and suppresses tumor neoangiogenesis, recapitulating the phenotype observed in chemerin-expressing tumors." (PMID 40867595, 2025). "The Chemerin-CMKLR1 axis is also involved in the recruitment of local macrophages, contributing to tumor microenvironment immune suppression." (PMID 40227577, 2025). "CD86, IL10RA, TNFSF13B, and CMKLR1 suppress effective anti-tumor immunity while simultaneously potentially promoting pro-tumor immune subsets – representing immunosuppressive signaling." (PMID 41006647, 2025). "G-protein-coupled receptors such as CMKLR1 also participate in lipid uptake and triglyceride synthesis, and pharmacologic inhibition of CMKLR1 has been shown to reduce lipid storage and suppress tumor growth." (PMID 41451091, 2025). "The chemerin/CMKLR1 axis is one of the main signal transduction pathways involved in tumor progression." (PMID 38280909, 2024). "In patients with viral hepatitis, the tumor and para-tumor expression of CMKLR1 protein was similar." (PMID 36979716, 2023). "CMKLR1 protein was found to be reduced in HCC tissues in comparison to the tumor adjacent tissues of European patients with NAFLD." (PMID 36979716, 2023). "Previously conducted studies found that RARRES2 acts as a secreted protein that recruits CMKLR1-expressing NK cells to tumor sites to exert tumor suppressive effects indirectly." (PMID 38269250, 2023). "It is possible that CMKLR1 localizes to the nucleus in different tumor cells, but further experiments have to prove this assumption." (PMID 36979716, 2023). "Comparison of the male patients with low, moderate, and high tumor CMKLR1 protein revealed that the T stage, lymph node invasion, and vessel invasion were significantly increased in the high versus the low CMKLR1 group." (PMID 36979716, 2023). "Comparison of the patients with low, moderate, and high tumor CMKLR1 proteins revealed that the T stage and blood vessel invasion were significantly increased in the high versus the low CMKLR1 group." (PMID 36979716, 2023). "Blocking the chemerin/CMKLR1 axis with 2-(α-naphthoyl) ethyltrimethylammonium iodide disrupted the mesenchymal network and suppressed tumor growth in GBM." (PMID 35459783, 2022). "Taken together, these results suggest that targeting the chemerin/CMKLR1 axis is an efficient strategy to decrease mesenchymal features and boost the anti-tumor immune environment in mesenchymal GBM." (PMID 35459783, 2022).
tumor (continued). "As a result, the cells expressing CMKLR1 are locally stimulated, resulting in a phenotype similar to that observed when chemerin is overexpressed in the tumor." (PMID 34638484, 2021). "CMKLR1 is expressed by endothelial cells, and the tumor angiogenesis is impaired in the context of bioactive chemerin overexpression." (PMID 34548907, 2021). "Reduced tumor formation in mice was connected to an altered profile of tumor-infiltrating cells and recruitment of NK (natural killer) cells in a CMKLR1-dependent way." (PMID 34068679, 2021). "The consequences of CCRL2 overexpression by tumor cells were partially reversed in chemerin KO, Cmklr1 KO, and Gpr1/Cmklr1 double KO mice but unaffected in Gpr1 KO mice." (PMID 34638484, 2021). "In the present work, we investigate the impact of CCRL2 expression by the host and tumor cells on the chemerin-CMKLR1 axis and its consequences on tumor progression." (PMID 34638484, 2021). "It recruits inflammatory cells through its G protein-coupled receptor CMKLR1 (Chemokine-like receptor-1), which is expressed by macrophages, dendritic cells, NK cells, and tumor cells." (PMID 34830179, 2021). "Its expression by tumor cells can significantly tune the effects of the chemerin/CMKLR1 system and act as a negative regulator of tumorigenesis." (PMID 34638484, 2021). "Cell types reported to express CMKLR1 and contributing to the tumor micro-environment include macrophages, myeloid and plasmacytoid dendritic cells, NK cells, endothelial cells, smooth muscle cells, and adipocytes." (PMID 34638484, 2021). "The tumor-infiltrating lymphocytes (TILs) were assessed in our study; however, the correlation between the TILs and concentration of CMKLR1 in tumor tissue was insignificant." (PMID 34946244, 2021). "Altogether, we conclude that the anti-tumoral properties of chemerin in these tumor graft models are entirely mediated by CMKLR1." (PMID 34548907, 2021). "We further investigated the role of CCRL2 on the activity of the chemerin-CMKLR1 axis in tumor progression by testing tumoral cell lines overexpressing CCRL2." (PMID 34638484, 2021). "In neuroblastoma cells, inhibition of chemerin-induced CMKLR1 signaling was found to reduce clonal growth and cellular viability in vitro and to inhibit tumor growth in animal experiments." (PMID 35008289, 2021). "CCRL2 and CMKLR1 are expressed by endothelial cells, and we demonstrated previously that chemerin expression by tumor cells inhibits tumor angiogenesis, thereby promoting cell death and a growth delay." (PMID 34638484, 2021). "Conditioned media from control transduced lines was unable to induce CMKLR1+ L1.2 cell chemotaxis, while conditioned media from chemerin-expressing tumor lines triggered robust migration comparable to recombinant, active chemerin (3 nM, R&D Systems)." (PMID 31139180, 2019). "In contrast to these anti-cancer effects, neuroblastoma tumor growth is reportedly reduced when chemerin/CMKLR1 signaling is blocked." (PMID 31905933, 2019). "Taken together, these data provide evidence that chemerin/CMKLR1 signaling promotes neuroblastoma development through direct effects on tumor cells and the tumor microenvironment." (PMID 31561459, 2019). "Use of these CMKLR1 tracers resulted in distinct target-specific DU4475 tumor uptake with 5.1% IA/g ([68Ga]Ga-DOTA-AHX-CG34), 3.3% IA/g ([68Ga]Ga-DOTA-KCap-CG34) and 6.2% IA/g ([68Ga]Ga-DOTA-ADX-CG34)." (PMID 31588246, 2019). "Analysis of ex vivo tumor tissue confirmed CMKLR1 expression in DU4475 xenografts by immunostaining, whereas A549 tumors showed no detectable antigen." (PMID 31588246, 2019). "Taken together, these results showed that chemerin enhanced CSCC cell migration and promoted tumor growth through chemerin/CMKLR1/CCRL2/GPR1 interactions and subsequent activation of MAPK pathway subtypes." (PMID 30555465, 2018).
tumor (continued). "Chemerin (RARRES2) is an endogenous innate leukocyte chemoattractant previously shown to recruit immune cells via its receptor CMKLR1 into the tumor microenvironment and thereby suppresses tumor growth." (PMID 30400822, 2018). "Chemerin, a ligand for CMKLR1 possesses a wide variety of characteristics attributed to tumor growth such as chemotaxis and cell adhesion, as well as cell survival and proliferation." (PMID 29221117, 2017). "In this regard, the pro-tumoral activity of G protein-coupled receptor 1 (GPR1) and CMKLR1 chemerin receptors has been recently demonstrated to induce FAAs uptake and the clear cell morphologic features in ccRCC, by modulation of tumor cells’ SREBP1c and CD36 expression." (PMID 40227577, 2025). "While decreased chemerin levels have been reported in HBV-associated HCC in Asian cohorts, increased expression in NAFLD-related and idiopathic HCC has been noted in European studies, despite consistent CMKLR1 downregulation across tumor types, potentially limiting downstream signaling." (PMID 41301712, 2025). "For CMKLR1, it is important to note that only tumor cell expressed protein was quantified." (PMID 36900088, 2023). "A lower expression of CMKLR1 in the tumor tissues of NAFLD patients may prevent chemerin from exerting its anti-tumor effects." (PMID 36979716, 2023). "In this context, it might be of interest to investigate the composition of tumor-infiltrating lymphocytes and their interaction with chemerin via CMKLR1 in further studies." (PMID 36900088, 2023). "Recent studies expounded that CMKLR1 expression was positively correlated with the tumor size of CRC patients, suggesting that CMKLR1 activity may facilitate tumor progression in CRC." (PMID 37958942, 2023). "In our study, both chemerin and CMKLR1 levels in tumor tissues positively correlated with estrogen receptor β (ERβ), which could be confirmed on the mRNA level for CMKLR1 and ESR2 by in silico analysis." (PMID 36900088, 2023). "In a study, the PC cells of a patient also expressed CMKLR1: as in PC cell lines, chemerin may act through CMKLR1 on tumor cells to modulate PTEN and PD-L1." (PMID 35203446, 2022). "Considering the autocrine effect of chemerin on activating NF-κB signaling in TAMs and GBM cells, targeting the chemerin/CMKLR1 axis in GBM could be expected to exert a similar tumor suppressive effect as that with NF-κB inhibition." (PMID 35459783, 2022). "We therefore tested whether the chemerin/ CMKLR1 system might influence tumor growth and progression by affecting the set of leukocytes recruited to the tumor microenvironment." (PMID 34548907, 2021). "To determine whether CMKLR1 is involved in the protective effects of chemerin, we tested the consequences of chemerin overexpression on the tumor graft models, using mice invalidated for CMKLR1." (PMID 34548907, 2021). "Furthermore, chemerin receptor CMKLR1 was detected at higher abundance in CRC tumor tissues than in margins." (PMID 35008289, 2021). "CMKLR1 and chemerin have recently been recognized as modulators of tumor proliferation." (PMID 33986665, 2021). "CMKLR1 might play a multifunctional role in CRC pathogenesis by influencing tumor budding and peritumoral lymphocytic infiltration." (PMID 34946244, 2021). "One of the radiotracers, 68Ga-DOTA-ADX-CG34, showed the highest tumor uptake with 6.2 ± 0.5% ID/g in CMKLR1-positive DU4475 (TNBC) xenograft models, while 68Ga-DOTA-AHX-CG34 presented the highest T/B ratio of 5.9 ± 0.7 at 1 h p. i., and 68Ga-DOTA-KCap-CG34 the lowest kidney and liver uptake." (PMID 33986665, 2021). "CMKLR1 expression was also described in endothelial cells, suggesting another mechanism by which chemerin may control tumor development." (PMID 34548907, 2021). "We hypothesized that CCRL2 (over)expressed by tumor cells might increase the local concentration of chemerin in the tumor and enhance the functional response of CMKLR1-expressing cells in the microenvironment." (PMID 34638484, 2021).
tumor (continued). "Some studies report that activation of CMKLR1 by chemerin may exert antitumoral effects via recruiting antitumoral immune cells such as NK cells and suppressing M2 macrophages involved in tumor invasion." (PMID 34946244, 2021). "In CRC, CMKLR1 was discovered at higher abundance in CRC tumor tissues than in margins." (PMID 35008289, 2021). "We found a significant difference in the levels of CMKLR1 between the tumor and margin tissues." (PMID 34946244, 2021). "CMKLR1 may therefore be a promising target for molecular imaging and targeted radionuclide therapy in overexpressing tumor entities." (PMID 31588246, 2019). "Protein levels of CMKLR1 were comparably reduced in the tumor tissues of both groups." (PMID 31905933, 2019). "In addition, tumor uptake was blocked by excess of unlabeled peptide (6.4-fold, 5.5-fold and 3.4-fold 1 h post-injection), further confirming CMKLR1 specificity." (PMID 31588246, 2019). "However, another report found that in melanoma, chemerin inhibited tumor growth in vivo by recruiting CMKLR1-expressing natural killer cells." (PMID 29279348, 2018). "However, the function of the chemerin/CMKLR1 axis in malignancies is probably tumor specific as both tumor promoting and tumor suppressing roles have been reported." (PMID 29221117, 2017). "Collectively, these findings indicate that targeting CMKLR1 expressed on stromal cells in addition to the tumor cells could be of therapeutic interest." (PMID 29221117, 2017). "Inhibiting CMKLR1 at a stage where the tumor has reached a certain size might therefore have a smaller impact." (PMID 29221117, 2017). "In addition, the expression of CMKLR1 positively correlated with the presence of tumor-infiltrating lymphocytes (TILs), with higher numbers of TILs in tumors with higher CMKLR1 expression, thereby providing a potential mechanism for the improved survival in the study." (PMID 40564073, 2025). "In addition, the authors identified the chemokine RARRES2 as a paracrine signal sent from fibroblasts to macrophages and from CAFs to TAMs, inducing upregulation of CMKLR1 and macrophage migration, based on cross-transcriptional patterns found in tumor and isolated co-culture systems." (PMID 38693304, 2024). "The main aim of our study was to determine whether the concentration of CMKLR1 in tissue is associated with microvessel density (MVD) in CRC and to assess its relationships with tumor histopathological parameters: budding and tumor-infiltrating lymphocytes assessment (TILs)." (PMID 34946244, 2021). "The majority of present data report down-regulation of chemerin in cancer tissue and suggest a tumor-suppressing role of chemerin in most cancer entities, being mediated by recruiting innate immune defenses and by growth-inhibitory downstream signaling by chemerin receptors CMKLR1 and GPR1." (PMID 31370263, 2019). "Therefore, the expression of CMKLR1 on tumor promoting immune cells could also play a significant role in the tumorigenesis process." (PMID 29221117, 2017). "CMKLR1, GPR1, and CCRL2, the primary cellular receptors for chemerin, can be found in both normal and tumor tissues." (PMID 40959100, 2025). "Chemerin is an important chemotactic agent that induces immune cell recruitment through its receptors CMKLR1, GPR1, and CCRL2, thereby inhibiting tumor growth." (PMID 40959100, 2025). "Increased CMKLR1 and MMP-9 expression in tumor tissue, along with links to VCAM-1, indicate that chemerin facilitates angiogenic and matrix-remodeling processes." (PMID 41301712, 2025). "Chemerin binds to the receptors CMKLR1, GPR1 or CCRL2 to recruit immune cells, which then regulate the immune inflammatory response of the body and assume antitumor and protumor roles in tumor progression through interactions with different pathways." (PMID 40959100, 2025).
tumor (continued). "Although RARRES2 has different expression patterns in different tumors, RARRES2 can promote GBM mesenchymal properties by inhibiting the ubiquitin‒proteasome degradation of CMKLR1, which indicates that RARRES2 can support tumor progression in GBM." (PMID 37246211, 2023). "Thus, CMKLR1 expression may be more related to hypoxia than to tumor angiogenesis." (PMID 34946244, 2021). "Rather, CMKLR1 and GPR1 expression levels vary across many orders of magnitude for most tumor types, while CCRL2 is completely missing from seven of the tested cancer cell lines." (PMID 35008289, 2021). "The aim of the study was to assess the CMKLR1 level in tumor and margin tissues of CRC in relation to histopathological parameters: microvessel density (MVD), budding, tumor-infiltrating lymphocytes (TILs), TNM scale, and grading." (PMID 34946244, 2021). "Chemerin’s main cellular receptors, chemokine-like receptor 1 (CMKLR1), G-protein coupled receptor 1 (GPR1) and C-C chemokine receptor-like 2 (CCRL2) are expressed in most normal and tumor tissues." (PMID 31370263, 2019). "There was also expression of GPR1 in most cancer cells although the intensity of staining was lower than CMKLR1; moreover, GPR1 was also expressed in myofibroblasts particularly those adjacent to tumor cells." (PMID 30719206, 2019). "Hybrid PET/MR imaging along with concomitant biodistribution studies revealed distinct CMKLR1-specific uptake (5.1% IA/g, 3.3% IA/g and 6.2% IA/g 1 h post-injection) of our targeted tracers in DU4475 tumor tissue." (PMID 31588246, 2019). "A separate study showed that chemerin inhibited migration, invasion, and metastasis of HCC cells via disruption of the CMKLR1/phosphatase and tensin homolog (PTEN) complex, allowing PTEN to exert its tumor suppressor activities." (PMID 31905933, 2019). "Chemerin is an important chemoattractant inducing immunocyte recruitment by its receptors CMKLR1, GPR1 and CCRL2, leading to suppression of tumor growth." (PMID 31370263, 2019). "For example, CD123+ pDCs were found to selectively express CCR2, CMKLR1, and CXCR3, receptors known to be involved in DC maturation, trafficking and recruitment at tumor sites whereas XCR1 and CX3CR1, were selectively expressed by CD141+ mDCs and CD1c+ mDCs." (PMID 29795118, 2018). "CMKLR1 may play a multifunctional role in CRC pathogenesis, potentially through its effects on tumor budding and peritumoral lymphocyte infiltration." (PMID 41006647, 2025). "Experimental activation of CMKLR1 with the chemerin analog CG34 enhanced colony formation, vascularization, and tumor growth in CRC models, while genetic and epigenetic analyses identified chemerin-associated regulatory loci within known CRC susceptibility regions." (PMID 41301712, 2025). "In this study, we investigated the cell-intrinsic role of CCRL2 in tumor cell behavior, independent of its established function in immune surveillance and chemerin/CMKLR1 signaling." (PMID 40867595, 2025). "Building on our previous work demonstrating that CCRL2 modulates tumor growth in vivo through the chemerin/CMKLR1 axis, we now show that CCRL2 also influences tumor architecture and inflammatory signaling from within the tumor cells themselves." (PMID 40867595, 2025). "SLC28A2, VIP, CMKLR1, MARCO, and NOD2 were detected at low levels in non-tumor and tumor cells." (PMID 38742117, 2024). "High chemerin and CMKLR1 proteins in European patients with HCC are related to adverse clinical parameters such as the T stage, vessel invasion, grading, and UICC stage, indicating a tumor-promoting effect of this receptor and its ligand." (PMID 36979716, 2023). "We further found that the anti-tumor effect of CMKLR1 blockade was not mainly derived from influences on GBM cell proliferation or apoptosis." (PMID 35459783, 2022).